EGFR (epidermal growth factor receptor)
Diseases named in the same sentence as EGFR in open-access papers (continued):
Sharing a sentence is not in itself a finding about the gene and the disease.
lymphangitis (3 papers, 2016 to 2024). Inflammation of the lymphatic vessels. "ALK-positive patients were significantly more likely to have more lymphangitis, compared to EGFR-positive patients (p = 0.049)." (PMID 27518729, 2016). "In this study, we found that EGFR mutations were associated with GGO, KRAS mutations were associated with solid tumors that had low tendencies to metastasize to the lung and pleura, and ALK rearrangements were associated with lymph node involvement and lymphangitis." (PMID 27518729, 2016). "Lymphangitis was significantly more common among ALK-positive patients, compared to EGFR-positive patients (p = 0.049)." (PMID 27518729, 2016).
lymphoid neoplasm (3 papers, 2019 to 2025). A neoplasm composed of a lymphocytic cell population which is usually malignant (clonal) by molecular genetic and/or immunophenotypic analysis. "Mutations in EGFR (p.V843I; COSV51767379) and ROS1 (p.R2269Q; COSV63862037) have been extensively documented in solid tumors, although they have been reported anecdotally in lymphoid neoplasms for ROS1 (COSMIC database)." (PMID 40067847, 2025).
malignant meningioma (3 papers, 2010 to 2025). "Recent studies have shown that high expression of vascular endothelial growth factor receptor (VEGFR), platelet-derived growth factor receptor (PDEGFR) and epidermal growth factor receptor (EGFR) is associated with malignant meningiomas and shorter progression-free survival." (PMID 40052125, 2025). "Finally, p-ERK and EGFR showed higher expression in malignant meningioma with high expression of CD47, which was verified by western blot." (PMID 37171006, 2023).
malignant phyllodes tumor (3 papers, 2018 to 2023). A phyllodes tumor with sarcomatous stroma. "Interestingly, we also identified one EGFRvIII-positive breast lesion without EGFR amplification or somatic mutation in the MAPP cohort and another separate case of malignant phyllodes tumor with reported EGFRvIII and EGFR amplification on testing performed outside our institution." (PMID 38201434, 2023).
Mucoepidermoid lung carcinoma (3 papers, 2020 to 2025). "It is being explored the use of target therapy in these situations, favored by the durable partial response of a patient with Mucoepidermoid lung carcinoma with an alteration of EGFR treated with gefinitib." (PMID 41568370, 2025).
mucosal melanoma (3 papers, 2020 to 2025). A melanoma that arises from a mucosal site. "In summary, our preliminary study highlights the possibility for future in vivo and clinical verification of the utility of MET and EGFR inhibitors as a potential therapeutic strategies in mucosal melanoma." (PMID 37679999, 2023). "Our findings indicate a potential therapeutic strategy based on EGFR and MET inhibitors in mucosal melanoma, which should be further evaluated in vivo and in clinical experiments." (PMID 37679999, 2023).
muscular dystrophies (3 papers, 2023 to 2026). "Understanding how different ligands influence EGFR signaling and receptor heterodimerization will be essential for developing new therapeutic options for muscular dystrophies." (PMID 41513629, 2026).
neck tumors (3 papers, 2018 to 2023). "Only 10% of the tested clinical head-and-neck-tumor samples showed high EGFR activity." (PMID 36769112, 2023).
necrotizing enterocolitis (3 papers, 2017 to 2025). Necrotizing enterocolitis (NEC) is a devastating disease that affects mostly the intestine of premature infants. "Epidermal growth factor (EGF) is a ligand of EGFR, and EGF supplementation has been shown to block autophagy in IEC-6 cells and in a neonatal rat model of necrotizing enterocolitis." (PMID 29403451, 2017).
neonatal respiratory distress syndrome (3 papers, 2013 to 2022). "In mammals, the EGFR plays an important role in lung maturation; EGFR deficiency results in a mild respiratory distress syndrome and delayed lung maturation." (PMID 35050380, 2022). "Dead EGFR-/- mice exhibited condensed and immature lung morphologies resembling neonatal respiratory distress syndrome." (PMID 23526992, 2013).
nephrotic syndrome (3 papers, 2013 to 2024). A collection of symptoms that include severe edema, proteinuria, and hypoalbuminemia; it is indicative of renal dysfunction. "We show that MC1R is the ACTH receptor being augmented in nephrotic syndrome, thereby promoting restoration of stressfibers in podocytes by inhibition of EGFR signaling." (PMID 30356069, 2018).
neurofibromatosis type 1 (3 papers, 2019 to 2021). A clinically heterogeneous, neurocutaneous genetic disorder characterized by cafe-au-lait spots, iris Lisch nodules, axillary and inguinal freckling, and multiple neurofibromas. "Gene expression-based subtypes are: proneural (PN) aberrations in the platelet-derived growth factor receptor alpha (PDGFRA), mesenchymal (MES) aberrations in neurofibromatosis type I (NF1), and classical (CL) aberrations in epidermal growth factor receptor (EGFR)." (PMID 31484350, 2019). "The EGFR MEK1/2 inhibitor combination is further supported by findings in treatment refractory PDAC patients who subsequently received combination erlotinib and selumetinib, a MEK1/2 inhibitor that recently received an orphan drug designation for neurofibromatosis type 1." (PMID 30921351, 2019).
non-melanoma skin carcinoma (3 papers, 2009 to 2023). "Our results suggest that CCHCR1 is expressed in non-melanoma skin cancers in association with EGFR and Ki67 in vivo." (PMID 19551138, 2009). "EGFR signaling has also been implicated in the pathogenesis of non-melanoma skin cancer." (PMID 19551138, 2009).
nonalcoholic steatohepatitis (3 papers, 2017 to 2025). "Exposure to a single dose of polychlorinated biphenyls (PCBs) and a 12-week high-fat diet (HFD) results in nonalcoholic steatohepatitis (NASH) in mice by altering intracellular signaling and inhibiting epidermal growth factor receptor signaling." (PMID 34548932, 2021).
Opportunistic infection (3 papers, 2009 to 2025). An infection that is caused by a pathogen that would generally not be able to cause an infection in a host with a normal immune system. "Determining the incidence of anti-EGFR therapy-related ILD in NSCLC is complicated by many factors, including the underlying neoplastic disease, adverse events caused by other chemotherapy agents, oxygen treatment, radiation therapy, and opportunistic infections." (PMID 19656374, 2009). "Existing case studies indicate that EGFR‐TKI‐treated EGFR‐mutant NSCLC patients may develop PTB or PTB reactivation, possibly related to non‐TB lesion area Mtb reactivation caused by LC or increased opportunistic infection risk due to tumor treatment‐induced immunosuppression." (PMID 40347011, 2025).
ovarian serous cystadenocarcinoma (3 papers, 2008 to 2020). A malignant serous cystic epithelial neoplasm arising from the ovary. "Only EGFR was significantly correlated with poor outcome (HR = 1.51, 95% CI 1.15–2, P = 0.0033) in ovarian serous cystadenocarcinoma, whereas SIRT1 predicted a good outcome (HR = 0.75, 95% CI 0.57–1, P = 0.047)." (PMID 32536817, 2020). "In another recent study including mutation analysis of exon 18,19 or 21 of the EGFR TK domain in a series of 198 ovarian serous cystadenocarcinoma no mutation was found." (PMID 18182111, 2008). "Further analysis revealed that EGFR was the potential target mRNA of LDHAP5, which may play an important role in ovarian serous cystadenocarcinoma." (PMID 32536817, 2020). "Pearson correlation analysis showed that EGFR (R = 0.16, P = 0.00072), PTEN (R = 0.098, P = 0.043), SIRT1 (R = 0.094, P = 0.013), RELA (R = 0.18, P = 0.00013) and CREB1 (R = 0.16, P = 0.00094) were significantly correlated with LDHAP5 expression in ovarian serous cystadenocarcinoma." (PMID 32536817, 2020).
parasitic infection (3 papers, 2017 to 2020). "Further studies will be needed to precisely identify the kinase sequences of parasite EGFR and its function during parasite infection." (PMID 29075245, 2017). "In the up-regulated proteins focal adhesion, various cancers, ECM-receptor interaction, EGFR/GRB2/KRAS (annotated here as dorso-ventral axis formation), and Gap and adherens junctions featured, as did pathways related to bacterial and parasitic infection." (PMID 32161586, 2020).
penile squamous cell carcinoma (3 papers, 2013 to 2025). "Early-phase clinical data from other epithelial malignancies, including penile squamous cell carcinoma, also support the safety and feasibility of EGFR-targeted probes for intraoperative use." (PMID 41346398, 2025).
Peptic ulcer (3 papers, 2015 to 2024). The term peptic ulcer refers to acid peptic injury of the digestive tract, resulting in mucosal break reaching the submucosa. "EGF and EGFR protein expression is involved in the re-epithelialization and peptic ulcer healing process, which is associated with the proliferation, differentiation and migration of gastric mucous surface epithelial cells." (PMID 25452787, 2015). "For instance, dysregulation of EGFR in gastric epithelial cells by another pathogen Helicobacter pylori has been shown to lead to gastric disorders, such as peptic ulceration and neoplastic transformation." (PMID 32887412, 2020). "Despite this finding, when the associations between the peptic ulcer-related factors and climate were studied, it was found that the expression of occludin, NOS and EGFR was significantly lower in the extreme cold climate than that in the extreme hot climate." (PMID 25452787, 2015). "The PPI network was constructed for the peptic ulcer genes, the constructed network to show the interactions between peptic ulcer targets proved that the following genes have the higher node degrees; AKT1, TNF, SRC, EGFR, ESR1, PTGS2, MMP9." (PMID 38728332, 2024).
periampullary adenocarcinoma (3 papers, 2016 to 2020). An adenocarcinoma that arises from the periampullary region. "In this translational study we investigated PODXL and EGFR and demonstrated a significant relationship between the overexpression of these proteins in pancreatic and other periampullary adenocarcinomas." (PMID 32587323, 2020). "In this study, we have evaluated the prognostic impact of EGFR, HER2 and HER3 in periampullary adenocarcinoma, by morphological type and adjuvant treatment." (PMID 27070783, 2016). "The aim of this study was therefore to examine the expression and prognostic value of EGFR, HER2 and HER3 in periampullary cancer, with particular reference to histological subtype." (PMID 27070783, 2016). "Expression of EGFR, HER2 and HER3, and amplification status for HER2 in pancreatobiliary and intestinal type periampullary adenocarcinoma." (PMID 27070783, 2016). "Therefore, the aim of this study was to analyse the expression and prognostic significance of EGFR, HER2 and HER3, with particular reference to morphological subtype, in a retrospective, consecutive cohort of 175 cases with periampullary cancer." (PMID 27070783, 2016). "The efficacy of treatments targeted at EGFR, HER2 and HER3 are not well studied in periampullary cancer, in particular in I-type tumours." (PMID 27070783, 2016). "Although none of the patients in this study had received EGFR-inhibiting treatment, the findings indicate that some RAS wild-type periampullary cancers of I-type may indeed benefit from such treatment." (PMID 32914025, 2019).
pharyngeal cancer (3 papers, 2015 to 2021). "As a HNSCC in vivo model, the expression of the target EGFR was evaluated in the human pharyngeal carcinoma cell line FaDu." (PMID 31906300, 2020). "We found a decreased expression of the EGFR and ErbB2 receptors only in tongue, salivary gland but not pharynx cancer cell lines." (PMID 34561494, 2021).
primary sclerosing cholangitis (3 papers, 2013 to 2023). "In contrast, the cholangiocytes from primary sclerosing cholangitis (PSC) livers exhibited elevated phospho-EGFR, with an approximately 5-fold increase vs. normal (NL), primary biliary cirrhosis (PBC) and Hepatitis-C virus (HCV) infected livers." (PMID 25915403, 2015). "Finally, we demonstrate that phospho-EGFR is elevated in the chronic cholestatic liver disease, primary sclerosing cholangitis (PSC)." (PMID 25915403, 2015). "Additionally, cholangiocytes from LPS-treated mouse livers and human primary sclerosing cholangitis (PSC) livers exhibited increased phospho-EGFR (p<0.01)." (PMID 25915403, 2015).
psychosis (3 papers, 2019 to 2023). "Finally, Dbp, Paqr5, Ptprb, and Tmc7 are involved in the regulation of circadian rhythm, progesterone signaling, repression of EGFR signaling pathways, and psychosis risk, respectively." (PMID 31164799, 2019). "Also, we found Milancipran, an anti-depressant of serotonin-norepinephrin class, which is used for the treatment of psychotic disorders and fibromyalgia with dubious results, and an erbstatin-analog, which is a EGFR inhibitor." (PMID 34260684, 2021).
pulmonary neuroendocrine tumors (3 papers, 2021 to 2025). "In contrast, in pulmonary neuroendocrine tumors, EGFR is prominently displayed on the cell membrane in approximately 48% of cases and is typically expressed at high levels." (PMID 38539512, 2024). "In addition to EGFR, the expression of delta-like ligand 3 (DLL3), an inhibitory Notch pathway ligand, has been identified in lung NETs." (PMID 40026252, 2025).
rapidly progressive glomerulonephritis (3 papers, 2016 to 2020). Inflammation of the glomeruli that is characterized by a rapid loss in renal function with glomerular crescent formation observed on biopsy; it is often seen in patients with concomitant autoimmune disease, like Goodpasture's syndrome or systemic lupus erythematosus. "In knockout animals, deletion of EGFR specifically in podocytes protects mice from glomerular damage in diabetic nephropathy and rapidly progressive glomerulonephritis (RPGN)." (PMID 29549365, 2018).
salivary gland adenoid cystic carcinoma (3 papers, 2015 to 2023). An adenoid cystic carcinoma arising from the salivary gland. "Furthermore, in a human salivary gland adenoid cystic carcinoma cell line SACC-38, EGCG (in concentrations of 5, 10, 20, 40, and 80 μM for 48 h) significantly decreased EGFR protein levels and inhibited EGFR phosphorylation." (PMID 37446908, 2023).
scleroderma (3 papers, 2019 to 2021). Scleroderma is a rare autoimmune connective tissue disorder characterized by abnormal hardening of the skin and, sometimes, other organs. "Based on these data, we predict that inhibitors of the Areg-EGFR-MEK signaling axis may be effective in treatment of scleroderma and other fibrotic diseases." (PMID 33622407, 2021).
silicosis (3 papers, 2022 to 2025). Silicosis is a respiratory disease caused by breathing in (inhaling) silica dust. "In our results, p-EGFR and p-SYK consistently increased with silicosis progression in the phosphoproteome data." (PMID 35551173, 2022). "Using this comprehensive dataset, phosphorylated EGFR and SYK were found to play significant roles in silicosis progression by regulating the extracellular matrix and production of inflammatory cytokines." (PMID 35551173, 2022). "Notably, our recent study revealed the aberrant pathways at protein phosphorylation levels in the lungs of silicosis mice and identified the phosphorylation of EGFR (p-EGFR) and SYK (p-SYK) as potential therapeutic targets in the progression of silicosis." (PMID 38641226, 2024). "Notably, the phosphorylation of EGFR (p-EGFR) and SYK (p-SYK) were identified as potential therapeutic targets in the progression of silicosis." (PMID 35551173, 2022). "Notably, gefitinib and fostamatinib, inhibitors of p-EGFR and p-SYK, effectively attenuated silicosis, suggesting a promising strategy for silicosis." (PMID 35551173, 2022). "Inhibition of p-EGFR and p-SYK by gefitinib and fostamatinib were found to effectively ameliorated the progression of silicosis via inhibiting p-EGFR mediated fibronectin production in fibroblasts and p-SYK mediated pro-inflammatory cytokines synthesis in macrophages." (PMID 35551173, 2022). "We further clarified the mechanisms of p-EGFR and p-SYK in the development of silicosis." (PMID 35551173, 2022).
skin changes (3 papers, 2017 to 2024). "EGFR inhibitors induce C–C motif chemokine ligand 5 (CCL5) in dermopathy." (PMID 38092882, 2023). "Although weight loss was similar in the two groups, the MEK/EGFR combination led to skin changes not seen with the palbociclib doublet." (PMID 28059068, 2017).
spindle cell neoplasm (3 papers, 2021 to 2024). A benign or malignant neoplasm characterized by the presence of neoplastic spindle cells. "We believe the reported cases represent a hitherto unrecognized variant of “NTRK-rearranged spindle cell neoplasms” of the uterine cervix with novel EGFR mutations." (PMID 39387892, 2024). "In summary, we report two cases of S100 and CD34 positive polypoid spindle cell tumors of the uterine cervix harboring EGFR mutation which we believe represents a hitherto unrecognized variant of “NTRK-rearranged spindle cell neoplasms” of the uterus." (PMID 39387892, 2024). "While the herein presented cases are most likely benign, the overall number of clinically tested and, accordingly, published cases of uterine NTRK-rearranged spindle cell neoplasms is low, and it is possible that a malignant variant with EGFR mutation simply awaits its first publication." (PMID 39387892, 2024). "When the immunoprofile is not consistent with that of common spindle cell tumors, immunostaining for FDC markers such as CD21, CD23, and CD35, as well as further immunohistochemistry for D2-40, CD68, EGFR, EBV, and BRAF can be helpful for the diagnosis and subtyping of FDCS." (PMID 34516525, 2021).
T-cell acute lymphoblastic leukemia (3 papers, 2019 to 2021). Acute lymphoblastic leukemia of T-cell origin. "MiR-150 appears to modulate sialylation of EGFR via the PI3K/Akt pathway in T-cell acute lymphoblastic leukemia, and circRNA_000203 was found to promote cardiac fibrosis by suppressing targets of miR-26b-5p, Col1a2 and CTGF." (PMID 33494070, 2021).
testicular cancer (3 papers, 2012 to 2025). A primary or metastatic malignant neoplasm that affects the testis. "Finally, activation of EGFR and estrogen signaling pathways was predicted for cluster #4 in both investigated testicular cancer collectives." (PMID 40011822, 2025). "Among them, 3 genes were approved by FDA for cancer diagnosis, including: EGFR, KLK3 (PSA) and AFP for the diagnosis of colon, prostate and testis cancers, respectively." (PMID 22761861, 2012).
thrombotic microangiopathy (3 papers, 2021 to 2025). The syndromes of microangiopathic hemolytic anemia, thrombocytopenia, and variable signs of organ impairment, due to platelet aggregation in the microcirculation. "A new adverse effect called haemolytic and uremic syndrome or thrombotic microangiopathy has been found for erlotinib, which is the first anti-EGFR drug to obtain market authorisation." (PMID 34885014, 2021).
tuberous sclerosis (3 papers, 2012 to 2025). Hereditary disease characterized by seizures, intellectual disability, developmental delay, and skin and ocular lesions. "Tuberous sclerosis complex is characterized by a mutation in TSC1 or TSC2 which activates the signal pathway of mTORC1/RUNX1/EGFR with loss of function." (PMID 36231025, 2022). "Here, we report that endosomal-localized EGFR/Ezrin complex interacts with and triggers the inhibition of the Tuberous Sclerosis Complex (TSC complex) in response to EGF stimuli." (PMID 39937579, 2025).
uterine sarcomas (3 papers, 2015 to 2024). "Consistently, pathway enrichment analysis showed activation and downregulation of EGFR-associated pathway in EOCs and uterine sarcomas, respectively." (PMID 31771620, 2019). "Similarly, another new small molecule inhibitor, CUDC-101, acts on EGFR, ERBB2, and HDAC, which are all potential targets in uterine sarcomas." (PMID 26576131, 2015).